ADAMTSL2 (ADAMTS like 2)
Diseases named in the same sentence as ADAMTSL2 in open-access papers:
ADAMTSL2 is named in the same sentence as 48 diseases in open-access papers, as found by Europe PMC text mining. Sharing a sentence is not in itself a finding about the gene and the disease. The quoted sentences say what the papers report.
geleophysic dysplasia (22 papers, 2010 to 2026). Geleophysic dysplasia is a rare skeletal dysplasia characterized by short stature, prominent abnormalities in hands and feet, and a characteristic facial appearance (described as "happy''). "Geleophysic dysplasia (GD) is caused by recessive mutations in ADAMTSL2 (a disintegrin and metalloprotease with thrombospondin type I motifs-2; GD1), or dominant mutations in FBN1 (GD2) or LTBP3 (GD3)." (PMID 41864337, 2026). "Because we previously observed increased bone width in another acromelic dysplasia model (geleophysic dysplasia due to Adamtsl2 deficiency), we measured the width of humeri and femora." (PMID 41034152, 2025). "Geleophysic dysplasia-1 (GD1) is an autosomal recessive disorder caused by ADAMTS-like 2 (ADAMTSL2) variants." (PMID 38300707, 2024). "ADAMTSL2 variant-espressing models&nbsp;replicate the phenotypic heterogeneity of geleophysic dysplasia in mice, with severity linked to impaired ADAMTSL2 secretion." (PMID 38300707, 2024). "As mutations in ADAMTSL2 are known to cause autosomal recessive geleophysic dysplasia, the patient is re-diagnosed with geleophysic dysplasia in terms of her genotype and phenotype." (PMID 36246610, 2022). "Most notably, mutations of human ADAMTSL2 have been causally linked to the musculoskeletal disorder Geleophysic Dysplasia, where patients present with severe short stature, joint immobility and cardiac valvular abnormalities." (PMID 29518972, 2018). "The outcome of ADAMTS17 transcriptional suppression on fibrillin-2 assembly was akin to that ascribed to ADAMTSL2, which is mutated in geleophysic dysplasia, another short-stature-brachydactyly condition." (PMID 28176809, 2017). "A mutation in ADAMTSL2 has previously been associated with geleophysic dysplasia (GD) [OMIM: 231050], where the phenotype includes joint limitation." (PMID 26879370, 2016). "ADAMTSL2 mutations cause human geleophysic dysplasia characterized by short stature, small hands and feet, stiff joints, and thick skin." (PMID 27857980, 2016). "Mutations in the secreted glycoprotein ADAMTSL2 cause recessive geleophysic dysplasia (GD) in humans and Musladin–Lueke syndrome (MLS) in dogs." (PMID 25762570, 2015). "Sequence analysis of a candidate gene at this locus, ADAMTSL2, which is responsible for the human TGFβ dysregulation syndrome, Geleophysic Dysplasia (GD), uncovered a mutation in exon 7 (c.660C>T; p.R221C) perfectly associated with MLS (p-value = 10−12)." (PMID 20862248, 2010). "Adamtsl2 is associated with Geleophysic dysplasia (OMIM: #231050)." (PMID 20214815, 2010). "For targeting SNPs in the human genome, we considered two common SNPs in the Indian population, rs2073874 (ADAMTSL2, C>T) and rs138739292 (AKAP9, G>A), which are linked to Geleophysic dysplasia 1 and Romano-Ward syndrome, respectively." (PMID 36752591, 2023). "The clinical phenotypes of geleophysic dysplasia (GD) observed in ADAMTSL2 mutant patients exceed a function of simply promoting mechanical stability of the ECM." (PMID 23874219, 2013). "It was also recently shown that Adamtsl2 regulates the bioavailabilty of TGF-β resulting in increased TGF-β activity in fibroblasts from Geleophysic dysplasia patients." (PMID 20214815, 2010). "• Tiptoe walking, in association with early findings including short stature, acromelia, and broad proximal phalanges on radiographs, may suggest ADAMTSL2-related geleophysic dysplasia." (PMID 42151490, 2026). "Clinical features may overlap Geleophysic Dysplasia 2, but the causing gene is the ADAMTS-like protein 2 gene (ADAMTSL2) that is involved in TGFβ bioavailability." (PMID 37443678, 2023).
liver fibrosis (4 papers, 2022 to 2024). "ADAMTSL2 has been linked to fibrosis in various contexts, including liver fibrosis in nonalcoholic fatty liver disease, cardiac fibrosis, and fibrosis in several organs in Musladin-Lueke syndrome." (PMID 38300707, 2024). "As differential levels of ADAMTSL2 in blood samples predict the onset and degree of liver fibrosis, efforts should be made to investigate ADAMTSL2 as blood biomarker of cardiac fibrosis, and possibly also other ADAMTSL molecules." (PMID 38324186, 2024). "This links ADAMTSL2 to liver fibrosis, with possible implications for other fibrotic diseases, and is supported by its upregulation in cardiac fibrosis." (PMID 38324186, 2024).
acromelic dysplasia (3 papers, 2021 to 2025). "ADAMTS10, ADAMTS17 and, ADAMTSL2 are also involved in the pathogenic mechanism of acromelic dysplasia." (PMID 34912367, 2021).
heart failure (3 papers, 2021 to 2024). Inability of the heart to pump blood at an adequate rate to meet tissue metabolic requirements. "Indeed, a recent machine-learning omics-based analysis of circulating proteins associated with poor outcomes in patients with heart failure identified ADAMTSL2 as one out of nine predictive proteins." (PMID 38324186, 2024). "In experimental heart failure, ADAMTSL2 and ADAMTSL3 are interesting candidates for in vivo overexpression, either as a transgenic mouse model, or via viral injections." (PMID 38324186, 2024). "In the present study, we investigated expression of ADAMTSLs in heart failure, and identified novel functions of ADAMTSL2 in CFBs." (PMID 34611183, 2021). "In particular, ADAMTSL2 mRNA and protein levels were robustly increased in both experimental and clinical heart failure." (PMID 34611183, 2021). "Specifically, we found that ADAMTSL2 was robustly up-regulated in clinical and experimental heart failure, and ADAMTSL2 was predominantly expressed by CFBs." (PMID 34611183, 2021). "Cardiac ADAMTSL2 mRNA was robustly increased in human and experimental heart failure, and mainly expressed by fibroblasts." (PMID 34611183, 2021). "Another aspect is their potential as circulating biomarkers, where ADAMTSL2 may be specifically promising for cardiac fibrosis and heart failure." (PMID 38324186, 2024). "Furthermore, up-regulation of the ECM glycoprotein ADAMTSL2 was observed in heart failure, which was found to inhibit TGF-β signaling in cardiac fibroblasts." (PMID 38814950, 2024). "Moreover, ADAMTSL2 was identified among nine predictive blood biomarkers for adverse outcomes in patients with heart failure, and as an independent biomarker for fibrosis in the liver." (PMID 38324186, 2024). "Insights from analysis of ADAMTSL2 in GD patients, heart failure patients, mouse models and cell cultures may suggest general principles applicable to ADAMTSLs whose function remains as yet undefined." (PMID 38324186, 2024). "Adamtsl2 showed the highest up-regulation with a four–eightfold increase during hypertrophic remodelling, and an eightfold increase at end-stage cardiac dilatation, suggesting a potential role in fibrosis and heart failure." (PMID 34611183, 2021). "Finally, from a translational perspective, we investigated ADAMTSL2 levels in hearts of patients with heart failure and assessed the effects of ADAMTSL2 in human adult CFBs (haCFBs)." (PMID 34611183, 2021). "Thus, the increased levels of Adamtsl2 observed in experimental heart failure was confirmed in human heart failure, and our findings from hfCFBs translated to ventricular haCFBs." (PMID 34611183, 2021). "We speculate that elevated levels of ADAMTSL2 in patients and mice with fibrosis and heart failure could be beneficial, similar to BNP." (PMID 34611183, 2021). "Biallelic ADAMTSL2 variants results in the connective tissue disorder Geleophysic dysplasia (GD, MIM 231050), which severely affects skeletal growth, muscle, joint and cardiac development, and leads to repeated respiratory infections, heart failure and early death for most patients." (PMID 38324186, 2024). "Interestingly, ADAMTSL2 was recently identified as a predictor of prognosis and adverse outcomes in patients with heart failure, which could be related to degree of cardiac fibrosis." (PMID 38324186, 2024). "Efforts to increase ADAMTSL2 experimentally during heart failure progression, e.g. with an AAV vector, should also be made to evaluate the effects of ADAMTSL2 in vivo." (PMID 34611183, 2021). "Collectively, these data suggest that ADAMTSL2 regulates ECM deposition and TGFβ signalling and may thus have an important role in cardiac fibrosis and heart failure." (PMID 34611183, 2021).
lysosomal storage disorder (2 papers, 2019 to 2024). "While this impairment in secretion may lead to intracellular alterations, resembling lysosomal storage disorders, it is the lack of functional ADAMTSL2 in the extracellular matrix that appears to be the primary mechanism underlying GD1." (PMID 38300707, 2024).
non-alcoholic fatty liver disease (2 papers, 2022 to 2024). "Further analysis identified the ADAMTSL2 protein and eight other proteins that are closely related to advanced fibrosis in adults with non-alcoholic fatty liver disease (NAFLD)." (PMID 35720415, 2022).
Weill-Marchesani syndrome (2 papers, 2019 to 2022). Weill-Marchesani syndrome (WMS) is a rare condition characterized by short stature, brachydactyly, joint stiffness, and characteristic eye abnormalities including microspherophakia, ectopia of the lens, severe myopia, and glaucoma. "ADAMTSL2 binds to fibrillin-1 and the N-terminal binding site encompasses a fibrillin-1 mutation which results in Weill Marchesani Syndrome (WMS)." (PMID 31226403, 2019).
aortic stenosis (1 paper, 2021). Aortic valve stenosis is a aortic valve disease caused by the incomplete opening of the aortic valve. "We determined ADAMTSL2 mRNA levels in myocardial biopsies from three cohorts of patients, namely aortic stenosis (AS), hypertrophic obstructive cardiomyopathy (HOCM) and dilated cardiomyopathy (DCM) vs. respective controls." (PMID 34611183, 2021).
Aqueductal stenosis (1 paper, 2024). Stenosis of the cerebral aqueduct (also known as the mesencephalic duct, aqueductus mesencephali, or aqueduct of Sylvius), which connects the third cerebral ventricle in the diencephalon to the fourth ventricle, which is between the pons and cerebellum. "Moreover, our study identifies the downregulation of specific genes, such as L1CAM, PCDH9, ISLR2, ADAMTSL2, and B4GAT1, which have been previously well characterized as playing an important role in congenital hydrocephalus and aqueductal stenosis." (PMID 39118132, 2024).
breast carcinoma (1 paper, 2022). "Downregulated MYOM2 was observed in a majority of clinical cases of breast cancer, however, the role of MYOM2, ADAMTSL2, and LARS in HCC development and prognosis remains unclear." (PMID 36276270, 2022).
breast tumors (1 paper, 2016).
cardiomyopathies (1 paper, 2023). "In humans and mice, elevated levels of ADAMTSL2 are seen in cardiomyopathies." (PMID 37048405, 2023).
congenital hydrocephalus (1 paper, 2024). Hydrocephalus that is present at birth. "Moreover, downregulation of multiple proteins associated with congenital hydrocephalus (e.g., L1CAM, PCDH9, ISLR2, ADAMTSL2, and B4GAT1) points to a possible shared molecular foundation between congenital hydrocephalus and iNPH." (PMID 39118132, 2024).
fibrosis (1 paper, 2021). the formation of excess fibrous connective tissue in an organ or tissue in a reparative or reactive process. "The phenotypic evidence from ADAMTSL2 mutations in humans, mice and dogs suggests that ADAMTSL2 could limit cardiac fibrosis, possibly through regulation of collagen and microfibrils." (PMID 34611183, 2021).
hepatocellular carcinoma (1 paper, 2024). A malignant tumor that arises from hepatocytes. "Univariate analysis showed that ADAMTSL2 expression was correlated with the prognosis of hepatocellular carcinoma (HCC)." (PMID 38814950, 2024).
Infertility (1 paper, 2023). "Therefore, together with the known infertility of stb/stb male mice, our present results revealed that Adamtsl2 contributes to the regulation of male and female reproductive function and development." (PMID 37656189, 2023).
keratoconus (1 paper, 2026). A degenerative, structural disorder of the eye, characterized by a cone-shaped protrusion of the cornea. "This paradoxical corneal thickening, contrasting with the stromal thinning characteristic of classical keratoconus, represents a novel ADAMTSL2-related corneal phenotype." (PMID 41664703, 2026).
Respiratory insufficiency (1 paper, 2024). "Our study reveals a notable association between the severity of ADAMTSL2 allelic variants and respiratory insufficiency." (PMID 38300707, 2024). "We found a reduction of survival and growth, abnormalities in craniofacial and skeletal anatomy, respiratory insufficiency, and cardiac abnormalities that correlate with the impairment of mutated Adamtsl2 secretion." (PMID 38300707, 2024).
steatosis (1 paper, 2024). Increased lipid within the cytoplasm of cells. "Of note, IGSF9, ADAMTSL2, KRT18, and RIDA were associated with both steatosis and fibrosis." (PMID 39426127, 2024).
type 2 diabetes mellitus (1 paper, 2023). A type of diabetes mellitus that is characterized by insulin resistance or desensitization and increased blood glucose levels. "As an exemplar of use as a non-invasive diagnostic, logistic regression establishes a composite model comprising four proteins (ADAMTSL2, AKR1B10, CFHR4 and TREM2), body mass index and type 2 diabetes mellitus status, to identify at-risk steatohepatitis." (PMID 37037945, 2023).
ventricular septal defect (1 paper, 2024). The presence of a defect (opening) in the septum that separates the two ventricles of the heart. "The severity is reflected in the Adamtsl2-/- mice, which have ventricular septal defects (VSD) and die after birth with severe bronchial occlusion and presumed respiratory failure." (PMID 38324186, 2024).
cancer (3 papers, 2021 to 2025). A tumor composed of atypical neoplastic, often pleomorphic cells that invade other tissues. "The study investigated the expression of ADAMTSL2 in both pan cancer and CRC, using data from The Cancer Genome Atlas (TCGA) database to assess its diagnostic value." (PMID 38814950, 2024). "The objective of this study was to investigate the different expression patterns of ADAMTSL2 in pan cancer and CRC, and to assess the diagnostic importance of ADAMTSL2 in CRC using data from The Cancer Genome Atlas (TCGA) database." (PMID 38814950, 2024). "ADAMTSL2 in CRC is negatively correlated with TMB and MSI, indicating that ADAMTSL2 may reflect the cancer immunogenicity of CRC." (PMID 38814950, 2024). "These genes were also connected with other genes notably deregulated in cancer as ANGPTL1, ADAMTSL2, PELI2 and EPCAM." (PMID 41231825, 2025). "Both genes are connected with other genes notably deregulated in cancer as ANGPTL1, ADAMTSL2, PELI2 and EPCAM." (PMID 41231825, 2025). "The high expression of ADAMTSL2 could promote the activation of ECM receptor interaction, MAPK signaling pathway, Wnt signaling pathway, and pathways in cancer, while the low expression of ADAMTSL2 could inhibit the biosynthesis of unsaturated fatty acid." (PMID 34603444, 2021).
genetic disorders (3 papers, 2012 to 2025). "The ADAMTS Like 2 (ADAMTSL2) mutation has been identified to be associated with different human genetic diseases." (PMID 38814950, 2024). "Mutations in ADAMTSL2 have been found in different human genetic disorders." (PMID 38814950, 2024). "All together, these related genetic disorders suggest that specific ADAMTSL (at least ADAMTSL-2 and -4) and ADAMTS (ADAMTS-10 and -17) proteins modulate fibrillin-1 function in the skeleton, skin, joints, muscle, and eye." (PMID 22242013, 2012). "The ADAMTSL2 gene is part of the ADAMTS (A Disintegrin and Metalloproteinase with Thrombospondin motifs) family, which plays a crucial role in the degradation of the extracellular matrix and has been linked to various human genetic disorders." (PMID 39996021, 2025).
tumor (3 papers, 2021 to 2024). "The high expression of ADAMTSL2 was associated with N stage (p < 0.001), pathologic stage (p < 0.001), age (p < 0.001), histological type (p < 0.001), and neoplasm type (p = 0.001)." (PMID 38814950, 2024). "The study explored potential regulatory networks involving ADAMTSL2, including its association with immune infiltration, immune checkpoint genes, tumor mutational burden (TMB) / microsatellite instability (MSI), tumor stemness index (mRNAsi), and drug sensitivity in CRC." (PMID 38814950, 2024). "Furthermore, we investigate the correlation between ADAMTSL2 and immune infiltration, immune checkpoint genes, tumor mutation burden (TMB), microsatellite instability (MSI), tumor stemness index (mRNAsi), and drug sensitivity in CRC." (PMID 38814950, 2024). "An increased level of ADAMTSL2 expression in patients with CRC was significantly associated with the pathologic N stage (p < 0.001), pathologic stage (p < 0.001), age (p < 0.001), histological type (p < 0.001), and neoplasm type (p = 0.001)." (PMID 38814950, 2024). "Low expression of ADAMTSL2 was presented in the tumor parts but was not related to lymph node metastasis and tumor stage compared with the normal parts." (PMID 35743687, 2022).
connective tissue disorder (2 papers, 2010 to 2021). A disease involving the connective tissue. "Four members of the ADAMTS superfamily, ADAMTS10, ADAMTS17, ADAMTSL2 and ADAMTSL4 have been implicated in connective tissue disorders, including ADAMTSL2, the cause of GD." (PMID 20862248, 2010). "Recessive loss-of-function ADAMTSL2 mutations cause geleophysic dysplasia (GD), an inherited connective tissue disorder resulting in severe musculoskeletal, pulmonary, and cardiac anomalies, with increased TGFβ levels and activity observed in patient-derived skin fibroblasts." (PMID 34611183, 2021).
cardiovascular disease (1 paper, 2025). "Within this context, the present work identified ADAMTSL2 and ACY1 as two aptamer-based protein mediators significantly associated with semaglutide-induced MASH resolution that are implicated in cardiovascular disease and fibrosis." (PMID 40691365, 2025).
infection (1 paper, 2020). The state of being infected such as from the introduction of a foreign agent such as serum, vaccine, antigenic substance or organism. "As a positive control and as expected, infection with Ad-DNSmad2 attenuated induction of Adamtsl2 mRNA in response to TGF-β." (PMID 33288795, 2020).
ADAMTSL2 also shares sentences with these, for which no sentence is quoted: Acromelia (1 paper); brachydactyly (1); colorectal cancer (1); dilated cardiomyopathy (1); dysplasia (1); geleophysic dysplasia 2 (1); glaucoma (1); Hajdu-Cheney syndrome (1); hypertrophic obstructive cardiomyopathy (1); Impotence (1); lymphoma (1); male infertility (1); musculoskeletal disorder (1); osteogenesis imperfecta (1); Romano-Ward syndrome (1); schistosomiasis (1); short-limb dwarfism (1); skeletal dysplasia (1); stenosis (1); thyroid (1); trichorhinophalangeal syndrome (1).